CTLA4 (cytotoxic T-lymphocyte associated protein 4)
Diseases named in the same sentence as CTLA4 in open-access papers (continued):
Sharing a sentence is not in itself a finding about the gene and the disease.
melanoma (continued). "Moreover, anti-PD-1 monoclonal antibodies indicate superior overall/recurrence-free survival versus anti-CTLA-4 agent for advanced melanoma." (PMID 33922038, 2021). "Blocking of these co-inhibitory molecules by monoclonal antibodies directed against for instance PD-1 and CTLA-4 (known as immune checkpoint inhibitor therapy) has evolved in recent years as a novel and sometimes very effective immunotherapy for cancers like melanoma or lung carcinoma." (PMID 33995373, 2021). "The immunotherapies aiming at PD-1 and CTLA-4 have been widespread applied for melanoma." (PMID 34531901, 2021). "Indeed, the CTLA-4 expression has been demonstrated on other slid cancers, such as non-small cell lung cancer, melanoma, and CRC." (PMID 34067631, 2021). "Therefore, we recruited melanoma patients before beginning ICI therapy (anti‐CTLA‐4, anti‐PD‐1, anti‐CTLA‐4 + anti‐PD‐1) and analyzed the immune cell composition and function of peripheral mononuclear blood cells using flow cytometry." (PMID 33449393, 2021). "To test whether tumor-specific splicing-derived neoepitopes may be associated to the patient response to immune therapy, we applied ISOTOPE to RNA-seq data from two cohorts of melanoma patient samples prior to treatment with anti-CTLA4 or anti-PD1." (PMID 34529669, 2021). "One patient with malignant melanoma was treated with nivolumab and ipilimumab (anti-CTLA-4 Ab)." (PMID 33927311, 2021). "In many cancers such as non-small cell lung cancer, melanoma, renal cell carcinoma, and hepatocellular carcinoma, immune checkpoint inhibitors such as CTLA4 inhibitors and PD-1 inhibitors have been shown to have significantly positive effects on patient survival." (PMID 34490109, 2021). "Herein, the urothelial cancer database (IMvigor210) consisting of anti-PD-L1 therapy and the malignant melanoma database (GSE91016) administered with anti-PD-1 and-CTLA-4 therapy were used to investigate the association between risk score and immunotherapeutic benefits." (PMID 34712244, 2021). "Immune checkpoint inhibitors, including monoclonal antibodies targeting cytotoxic T lymphocyte-associated antigen 4 (CTLA4), programmed cell death 1 (PD1), or PD1 ligand (PD-L1), are effective in the treatment of various types of cancer, especially melanoma and lung cancer." (PMID 34944392, 2021). "Thus, checkpoint inhibitor (CKI) antibodies blocking the function of co-inhibitory T cell receptors (e.g., CTLA-4 and PD-1) have proven powerful in reviving “exhausted” immune responses in patients with melanoma and other cancers." (PMID 34743688, 2021). "As a consequence, immunotherapy based on blocking co-inhibitory receptors such as CTLA-4 and PD-1 expressed on the T-lymphocyte surface has emerged as a powerful strategy in melanoma treatment with the development of several checkpoint blocking antibodies such as Ipilimumab or Pembrolizumab." (PMID 33789714, 2021). "While melanoma and non-small cell lung cancer (NSCLC) patients have seen a great benefit from targeting immune checkpoint inhibitors such cytotoxic T lymphocyte-associated protein-4 (CTLA-4) or programmed cell death protein 1 (PD-1), EOC patients have only exhibited response rates of 10–15%." (PMID 33747935, 2021). "Similarly, melanoma patients being treated with anti-CTLA4 with lower levels of MDSCs following their first infusion had increased overall survival compared to patients with higher circulating MDSCs." (PMID 34944914, 2021). "Previous research has found that DNA methylation of CTLA-4 could predict response of anti-CTLA-4 and anti-PD-1 immune checkpoint blockage in melanoma." (PMID 34093667, 2021). "Notably, EZH2 inactivation reversed the drug-resistant phenotype and amplified the effects of anti-CTLA-4 and IL-2 immunotherapy in melanoma mouse models, thus blocking CM growth and dissemination." (PMID 34575678, 2021).
melanoma (continued). "However, immunotherapy is currently changing the landscape of melanoma treatment; immunomodulatory therapies, such as anti-PD-1 and anti-CTLA-4 antibody drugs, are the standard of care for patients with metastatic or unresectable melanoma." (PMID 34526609, 2021). "Indeed, Type I IFN signaling was shown to play a role in inducing inflammatory responses in B16 melanomas locally treated with oncolytic Newcastle disease virus combined with systemic CTLA4 blockade." (PMID 34571733, 2021). "Given that multiple targeted immune checkpoint blockade therapies, especially PD-1 and CTLA4, have shown significant efficacy in melanoma treatment, SERP1 expression levels in SKCM patients may also influence the efficacy of immunotherapy." (PMID 34613934, 2021). "Since anti-CTLA-4 (ipilimumab) was approved for melanoma treatment, which promotes T-cell activation by blocking the interaction of CTLA4 with CD80 and CD86, the clinical successes achieved by blocking CTLA-4 and PD-1 have inspired further exploration of the potential of ICB therapies." (PMID 33596985, 2021). "One might be the therapeutic combination with antibodies against PD-1 and CTLA-4 in BC, that in other cancers, such as melanoma, contributed to improved patient survival." (PMID 34829916, 2021). "A study indicated that increased CD8+ T cell trafficking contributes to anti-programmed-death 1 (PD-1)/CTLA-4 therapeutic efficacy against melanoma metastasis and may represent an effective immunotherapy strategy." (PMID 34136377, 2021). "Moreover, transcriptomic and immune profiling were performed on 158 tumor biopsies from melanoma patients treated with anti-PD-1 monotherapy or combined anti-PD-1 and anti-CTLA-4 therapy." (PMID 34360781, 2021). "Moreover, a positive correlation between the high expression of IDO and clinical response to anti-CTLA-4 therapy in melanoma has been reported." (PMID 34073463, 2021). "Similarly, the antibody targeting macrophage receptor with the collagenous structure (MARCO), by crosslinking the inhibitory FcgRIIB on TAMs, synergistically increases anti-CTLA4 immunotherapy in melanoma and colon cancer mouse models." (PMID 34476174, 2021). "Moreover, in one study, it was demonstrated that the expression of PD-L1 on histiocytes in patients with ovarian cancer and melanoma correlated with the efficacy of treatment with either anti-PD-1 alone or in combination with anti-CTLA-4." (PMID 33802174, 2021). "Study shows that PD-1 pathway blockade is more efficient than CTLA-4 blockade in advanced melanoma." (PMID 34539412, 2021). "Melanoma cells induce Tregs to overexpress various inhibitory checkpoint receptors, including programmed cell death protein 1 (PD-1), CTLA-4, T cell immunoglobulin and mucin domain-containing protein 3 (TIM-3), LAG-3, and T cell immunoglobulin and ITIM domain (TIGIT)." (PMID 34806028, 2021). "Combination of bicarbonate, which neutralizes tumor acidity, with routinely used in melanoma anti-CTLA4 or anti-PD-1 therapy significantly improved the antitumor effects of these drugs in the murine melanoma model, which was resistant to bicarbonate monotherapy." (PMID 33918883, 2021). "To further identify more novel predictive biomarkers, we performed data analysis using several public cohorts and found that MAP2K1/2 mutations might be a potential predictor for the clinical benefits of anti-CTLA-4 therapy in advanced melanomas." (PMID 35069558, 2021). "Clinical use of ICIs began with ipilimumab, a CTLA-4 inhibitor, for malignant melanoma." (PMID 35008367, 2021). "Similarly, 198 patients with advanced melanoma were recruited in another phase II trial and the combination of T-Vec and ipilimumab (anti-CTLA4 mAb) showed a superior ORR than ipilimumab alone (39% vs. 18%)." (PMID 33985527, 2021). "The inhibitor of CTLA4-ipilimumab has been approved by FDA for treating melanoma." (PMID 35127742, 2021).
melanoma (continued). "Indeed, robust antitumor responses were achieved with local chemotherapy combined with a CTLA-4 blockade in murine models of melanoma and prostate cancer." (PMID 33859948, 2021). "Moreover, combining anti-CTLA-4 with low doses of DNMTi proved to be an effective strategy in augmenting the immunotherapy efficiency in a mouse melanoma model." (PMID 34575678, 2021). "The predictive value of CTLA-4 mRNA and protein expression in melanoma remains ambiguous." (PMID 33196890, 2021). "Our data are also supported by data from the neo-adjuvant setting where a single injection of pembrolizumab in resectable stage III or IV melanoma patients resulted in the expansion of Ki67+ PD-1+ CTLA-4+ CD8+ T-cells in the peripheral blood of patients 7 days post injection." (PMID 34071888, 2021). "Based on the knowledge of the melanoma biology and its immunogenicity, new therapeutic strategies have been developed with antibodies directed to specific targets, including anti-PD-1 and anti-CTLA-4." (PMID 34066146, 2021). "In melanoma patients treated with anti-CTLA-4, a higher percentage of circulating mature NK cells is correlated with improved overall survival, and NK cells isolated from responsive patients have increased cytolytic activity compared to NK cells isolated from non-responders." (PMID 34376232, 2021). "More recent trials have shown superior anti-tumor efficacy with the dual combination of CTLA-4 and PD-1 blockade in melanoma, suggesting concurrent administration may be a beneficial therapeutic strategy; although with increased risk of toxicities." (PMID 34025662, 2021). "As for the immunosuppressive effects of melanoma, CTLA4 was significantly increased in the tumor in patients with metastatic melanoma, consistent with the current efficacy of clinical application of the anti-CTLA4 antibody for advanced melanoma." (PMID 33669410, 2021). "Besides the expression of CTLA-4 on immune cells, the CTLA-4 can also be highly expressed on the cell surface of human melanoma cells." (PMID 33692796, 2021). "TIDE score is a good predictor for anti-PD1 and anti-CTLA4 therapy in melanoma." (PMID 34395521, 2021). "Interestingly, tumor mutation load is significantly correlated with the clinical outcome of anti-CTLA4 antibody and adoptive T-cell treatment in melanoma." (PMID 33787673, 2021). "Similarly, the discovery of essential checkpoint receptors (including CTLA-4 and PD-1/PD-L1) and their role in immune evasion in cancers, including melanoma, reinvigorated the effort to develop immunotherapies that have proved crucial in prolonging survival." (PMID 34831002, 2021). "Furthermore, ipilimumab (a CTLA-4 blocking antibody) efficacy in melanoma patients positively correlated with increased CD56 transcript expression in post-treatment tumor biopsies." (PMID 35082797, 2021). "CTLA-4 blocking or 4-1BB activating antibodies can increase some murine tumors rejection, but they are unsuccessful to treat tumors with poor immunogenicity such as B16 melanoma as single factors." (PMID 34267616, 2021). "Targeting immune checkpoints provide novel insights into cancer therapy, and several immune checkpoint inhibitors, such as PD-1/PD-L1 and CTLA-4 inhibitors, have been used for the treatment of multiple cancers, including melanoma, kidney cancer and non-small cell lung cancer." (PMID 34631703, 2021). "Meanwhile, melanoma patients treated with CTLA-4 inhibitors had a low response ratio (25%)." (PMID 34220837, 2021). "Ipilimumab, initially approved for treatment of stage III/IV melanoma, achieves therapeutic action by blocking the cytotoxic T lymphocyte antigen 4 (CTLA-4) from binding to its ligands B7.1 and B7.2, effectively functioning as an inhibitor of IL-2 production and T-cell differentiation." (PMID 34771675, 2021).
melanoma (continued). "Inspired by the phenomenal success of inhibitors that block CTLA-4 and PD-1 in melanoma, pharmaceutical industries have been marketing three FDA-approved monoclonal antibody drugs, Yervoy (Ipilimumab, against CTLA-4), Keytruda (pembrolizumab, against PD-1), and Opdivo (nivolumab, against PD-1)." (PMID 34575998, 2021). "In recent years, despite many research results in the field of immune cell infiltration in solid tumors and the development of immune checkpoint inhibitors such as anti-PD-1, CTLA-4 for the Treatment of Renal Cell Carcinoma, Metastatic Melanoma, and Non-Small Cell Lung Cancer." (PMID 34777462, 2021). "Thus, the subgroups with different risk scores were explored in another published dataset containing 47 patients with melanoma who respond to immune checkpoint inhibitors (anti-PD-1 or anti-CTLA-4)." (PMID 34124058, 2021). "Targeting CTLA-4 (ipilimumab), PD-1 (nivolumab) or its ligand PD-L1 (pembrolizumab) has been shown to be extremely effective in the treatment of a variety of advanced cancers including melanoma and non-small cell lung cancer." (PMID 34658896, 2021). "High levels of this C4G biomarker at baseline could identify melanoma patients responding to anti-CTLA-4 treatment and when combined with low PRO-C3, this biomarker combination could identify additional responding patients." (PMID 34656158, 2021). "Moreover, the administration of CTLA-4 blockade can induce anti-tumor responses against CNS metastasis in patients suffering from melanoma." (PMID 32902664, 2021). "Early promising results of anti-CTLA-4, ipilimumab, and anti-PD-1, pembrolizumab and nivolumab, demonstrated that ipilimumab compared favorably to the current standard melanoma therapies of the time including gp100 peptide vaccine and improved overall survival (OS)." (PMID 35087529, 2021). "Indeed, reduced MHC class I immunostaining and gene expression in pretreatment biopsies from anti-CTLA-4 treated melanoma patients predicts resistance to therapy and reduced survival." (PMID 33547395, 2021). "Copy number deletion of the IFN gene cluster may also leads to a worse prognosis in melanoma patients and could be useful as a prognostic marker to predict resistance to immunotherapy (e.g., anti-CTLA4 treatment)." (PMID 34555656, 2021). "NGFR expression was higher in nonresponders to anti-PD-1 or anti-PD-1 and anti-CTLA-4 combinations and was associated with low T cell infiltration in melanoma." (PMID 34827646, 2021). "Similarly, upregulation of an IFN-γ-responsive gene expression signature appears to be important for the clinical success of anti–CTLA-4 mAb, as evidenced by the analysis of tumor specimens from melanoma patients treated with Ipilimumab." (PMID 33777008, 2021). "The combination of anti CTLA-4 and anti PD-1 is now approved as the first line therapy for advanced melanoma patients; however, the toxicities have limited the use of this combination, trials are ongoing to vary the dose and interval of dosing to reduce toxicity." (PMID 33859638, 2021). "A clinical trial (NCT03341143) was conducted to assess the effects of FMT in melanoma patients resistant to anti-PD-1 treatment whether alone or in combination with anti-CTLA-4." (PMID 34827646, 2021). "Also, combination therapies targeting PD-1/PD-L1 and CTLA-4 are very effective in patients with malignant melanoma, microsatellite instability high colorectal cancer, and are being investigated in many ongoing clinical trials in patients with HCC." (PMID 34956912, 2021). "Furthermore, in a mouse model of melanoma, vaccine-activated T effector cells potently synergized with a checkpoint blockade of CTLA-4 and PD-L1, leading to complete tumor regression, even under primary resistance to dual checkpoint blockade." (PMID 33801815, 2021). "A TLR9 binding CpG-ODN adjuvant with a systemic anti-CTLA-4 antibody could increase the survival of mice bearing poorly immunogenic B16 melanoma." (PMID 34917131, 2021).
melanoma (continued). "However, the combination treatment with TA99 and blockade of CTLA4 resulted in a significant reduction in the number of melanomas in the lungs of the majority (4/5) of treated animals." (PMID 33520112, 2021). "Moreover, an increased effector CD8+ T-cell:Treg ratio within the tumour infiltrating lymphocyte (TIL) population has been shown to be a crucial predictor of anti-CTLA-4’s clinical efficacy in melanoma patients." (PMID 34944851, 2021). "In addition, TMB significantly contributes to a sustained clinical benefit from CTLA-4 blockade in melanoma." (PMID 34620200, 2021). "In addition, pituitary autoantibodies are detected in mice and melanoma patients after injection of anti-CTLA4 antibody." (PMID 35154081, 2021). "The second hypothesis was later confirmed on tumor biopsies from patients with melanoma experiencing transient progression on a CTLA-4 inhibitor, showing an acute inflammatory reaction with lymphocyte infiltration." (PMID 34733781, 2021). "Additionally, AURKA and AURKB expression levels were significantly inversely correlated with T-cell markers in a dataset of melanoma samples derived from patients treated with anti-CTLA4 therapy." (PMID 33123754, 2021). "To date, immunotherapies using PD-1/PD-L1 or CTLA-4 antagonistic antibodies have shown promising outcomes in various cancers such as melanoma, liver cancer and non-small cell lung cancer, thereby establishing immunotherapy as one of the most promising new therapeutic approaches." (PMID 34513864, 2021). "Disappointingly, the anti-CTLA-4 treatment’s effects on Treg cells remain inconclusive: While a reduction in tumour-infiltrating Tregs has been observed in some melanoma patients, other studies on melanoma, prostate and bladder tumours have reported no such depletion." (PMID 34944851, 2021). "Ipilimumab, an anti-CTLA4 antibody, was approved for treatment of melanoma in 2011." (PMID 33985527, 2021). "CTLA-4 and PD-1 blockade combination could increase effector T-cell infiltration into B16 melanoma in mice." (PMID 34917131, 2021). "Therefore, inhibiting the axis between cancer and immune cells through antibodies directed at CTLA-4/PD-1 leads to the invaluable improvement in treatment efficacy of numerous malignant tumors especially melanoma, lung cancer, and breast cancer." (PMID 34440813, 2021). "Interestingly, in patients with melanoma, lower levels of CD56dim NK cells were also found, which increased after treatment with ipilimumab, the first approved anti-CTLA-4 mAb." (PMID 33572396, 2021). "Interestingly, ipilimumab, a fully humanized monoclonal antibody against CTLA-4, has been shown to reduce Treg infiltration in responders among melanoma patients." (PMID 33602289, 2021). "Moreover, patients with melanoma with high C5orf58 expression who received single anti-PD-1 monotherapy or anti-CTLA-4 monotherapy also showed a worse drug response, resulting in worse progression-free survival." (PMID 34178688, 2021). "However, while not significant overall, the HLA B44 supertype and germline HLA-I evolutionary divergence were significant in the anti-CTLA-4 melanoma cohorts." (PMID 34572771, 2021). "Recently, we showed that CTLA4 promoter methylation predicts response to ICB in melanoma." (PMID 34446578, 2021). "The earliest reports that CD4+ T cells could be directly cytotoxic to patient tumor cells involved isolation of circulating CD4+ T cell clones specific for NY-ESO-1 in melanoma patients treated with ipilimumab (anti-CTLA-4)." (PMID 34910940, 2021). "Furthermore, ipilimumab induced ADCC by pbNK cells from healthy volunteers against CTLA-4+ melanoma cells." (PMID 33572396, 2021). "In another study, post-treatment intratumoral B cell counts and B cell associated gene signatures strongly correlated with response to anti-PD-1 +/- anti-CTLA-4 in locally advanced melanoma patients exposed to neoadjuvant ICI therapy, whilst B cell counts at baseline did not." (PMID 33602280, 2021).